TNF (tumor necrosis factor)
Diseases named in the same sentence as TNF in open-access papers (continued):
Sharing a sentence is not in itself a finding about the gene and the disease.
COVID-19 (continued). "Previous studies have shown that elevated levels of proinflammatory cytokines, such as IFN-γ, TNF-α, IL-6 and IL-8, are associated with severe lung injury and adverse outcomes, suggesting that the magnitude of cytokine storm is associated with COVID-19 severity." (PMID 34829345, 2021). "When considering the role of cytokines in COVID-19 specifically, it has been observed that higher levels of IL-6, IL-8 and TNF, at the time of admission, were associated with significantly lower rates of survival after adjusting for demographics and comorbidities as confounding variables." (PMID 34341776, 2021). "We consecutively included patients during the first peak of the COVID-19 epidemic in Brazil and analyzed the expressions of genes encoding interleukin (IL)-1β, IL-6, IL-8, IL-10, IL-12A, IL-12B, and tumor necrosis factor-α in peripheral blood mononuclear cells." (PMID 33819170, 2021). "Altogether, our data suggest that high levels of circulating IL-6, TNF, and IL-10 might be associated with the severity of COVID-19, while only an increased level of IL-6 might be related to the severity of SARS and MERS." (PMID 34046036, 2021). "Meanwhile, there is an increase in the levels of inflammatory markers such as ferritin, interleukin (IL) 6, Interferon-inducible protein 10 (IP-10), MCP1, tumour necrosis factor alpha (TNF-α) and D-dimer, all of which have been associated in mortality of COVID-19 and reported in various studies." (PMID 32947974, 2020). "COVID-19 infects the upper and lower respiratory tract, causing the release of pro-inflammatory cytokines such as interleukin 1β (IL-1β), tumor necrosis factor (TNF), and IL-6." (PMID 32802622, 2020). "We further found that elevated and a trend of a continued increase in cytokine levels, including IL-2R, IL-6, IL-8, IL-10 and TNFα, and decreased lymphocyte subsets, especially helper T cells, suppressor T cells and NK cells, were associated with a poor prognosis of COVID-19." (PMID 33365277, 2020). "Moreover, higher levels of IFNγ TNFα, IL-2, and IL-10 have been associated with COVID-19 severity, further supporting a pathogenic role." (PMID 33634100, 2020). "The markedly increased serum concentrations of interleukin (IL)-2R, IL-6, tumor necrosis factor (TNF)-α, and IL-10 that occur more in patients with severe COVID-19 than in moderate cases also suggests an association between the cytokine storm and the disease severity." (PMID 32570850, 2020). "Moreover, single cell analysis of PBMCs has reported the presence of a monocyte subset unique to severe COVID-19 patients that is enriched in genes encoding a range of cytokine storm related cytokines such as IL-1β, IL-6, and TNF-α." (PMID 33123152, 2020). "•It is uncertain whether anti-TNF therapy increases the risk of infection with SARS-CoV-2 or COVID-19." (PMID 32520223, 2020). "This may be due to increased expression of cytokines, including interleukin (IL)-2, IL-6, IL-7, tumor necrosis factor, granulocyte colony-stimulating factor, interferon-gamma, and free radicals associated with the severity of COVID-19." (PMID 32953353, 2020). "This study aimed to determine whether patients with elevated CRP, TNFα, and IL-6 levels may be at increased risk for severe infection and liver damage of COVID-19." (PMID 33244370, 2020). "Severe COVID-19 is associated with increased serum inflammatory cytokine levels including IL-1, IL-6, granulocyte-colony stimulating factor (G-CSF), interferon-γ inducible protein 10 (IP-10), and tumor necrosis factor-α (TNF-α)." (PMID 32655582, 2020). "Importantly, increased levels of IFN-γ, IP-10, MCP-1 and TNF-α are associated with severity of disease in in COVID-19 patients." (PMID 32803199, 2020). "However, the severe COVID-19 cases showed an increase in IL-6, IL-2R, IL-10, and TNFα secretion associated with a severe decrease in T cells, particularly CD4+ T cells." (PMID 32793246, 2020).
COVID-19 (continued). "SARS-CoV-2 infection of human monocytes in vitro recapitulates most of the pattern of inflammatory mediator production associated with COVID-19 severity, including the enhancement of the IL-6 and TNFα levels, and the consistent cell death, measured by LDH release." (PMID 33326472, 2020). "However, Patients infected with SARS-CoV-2 who have the TNF-α gene variant (rs1800629) are protected from developing COVID-19 moderate and severe outcomes, as well as from presenting low concentrations of some pro-inflammatory cytokines and chemokines (IL-6, CCL2, and CXCL-10)." (PMID 40881695, 2025). "Additionally, in an analysis of human dermal microvascular endothelial cells exposed to plasma from patients with acute COVID-19, DF suppressed cellular pathways associated with endothelial activation by COVID-19 plasma, including TNFα signaling, IL-17 signaling, endothelin activity, and fibrosis." (PMID 40723876, 2025). "In fact, COVID-19-associated male infertility may involve a decrease in testosterone levels and spermatogenesis through shifts in cytokines such as IL-4, IL-6, IFNγ, and TNFα." (PMID 40507130, 2025). "This study significantly advances our understanding of COVID-19 severity by evaluating a comprehensive panel of cytokines and clinical markers, confirming the robust association between elevated levels of IL-1β, IL-6, IL-8, IL-10, IL-17A, IL-23, TNF-α, and IFN-α with critical disease outcomes." (PMID 39861879, 2025). "Additionally, mebendazole may exert immunomodulatory effects by downregulating pro-inflammatory cytokines such as IL-6 and TNF-α, which are implicated in the cytokine storm associated with severe COVID-19." (PMID 40426524, 2025). "In addition, according to a literature-based pathway, anxiety may upregulate multiple cytokines (IL6, IL10, and TNF) and angiotensin II, which are associated with harmful effects during COVID-19." (PMID 40766923, 2025). "Furthermore, ivermectin modulates host immunity by downregulating nuclear factor kappa B (NF-κB) signaling and reducing levels of key pro-inflammatory cytokines such as IL-6 and TNF-α, which are implicated in the cytokine storm observed in severe COVID-19 cases." (PMID 40426524, 2025). "Previous studies have shown that cytokine storms in patients with COVID-19 and other severe infections are significantly associated with high mortality, particularly highlighting the pivotal roles of pro-inflammatory factors such as IL-6 and TNF-α in dysregulated inflammation." (PMID 39774553, 2025). "Although TNF-α inhibitors have been considered as potential therapeutic agents, evidence suggests that their use may raise the risk of co-infections (such as bacterial and mycobacterial) in COVID-19 patients, potentially worsening the disease." (PMID 40661964, 2025). "Additionally, systemic inflammation caused by COVID-19, such as complement C3 decrease and IL-6, TNF-α increase, are risk factors for long-term lung symptoms and leads to diffuse parenchymal changes in the lungs, including alveolar damage, exudation, and pulmonary fibrosis." (PMID 39149538, 2024). "Severe COVID-19 cases have been associated with a cytokine storm featuring increased levels of proinflammatory cytokines like interleukin (IL)-1, IL-6, and tumor necrosis factor (TNF)-α, which may promote neuroinflammation and neurodegeneration." (PMID 39456822, 2024). "Our results uncover an unexpected mechanism by which type I interferon-mediated TNF-α signaling exacerbates the disease severity and will aid in the development of novel therapeutic strategies to treat respiratory virus infection and associated diseases such as influenza and COVID-19." (PMID 39652608, 2024). "Previous studies have shown that the severity of COVID-19 is linked to the levels of interleukin(IL)-2, IL-6, IL-8, and tumour necrosis factor-α (TNF-α), and alterations in the expression of these inflammatory cytokines may occur in the early stages of SARS-CoV-2 infection." (PMID 38726341, 2024).
COVID-19 (continued). "Therefore, inhibition of TNF-α in patients with COVID-19 may reduce many of these pathogenic cytokines." (PMID 39118801, 2024). "Also, the level of pro-inflammatory cytokines, including TNF-α and IL-6, that are observed in cytokine storm can be regulated by Withania somnifera suggesting the potential role of Withania somnifera in managing disease progression associated with COVID-19." (PMID 38794167, 2024). "Moreover, COVID-19 is associated with a cytokine storm, which is characterized by the overproduction of pro-inflammatory cytokines, such as interleukin-6 (IL-6) and tumor necrosis factor-alpha (TNF-α)." (PMID 38090596, 2023). "Interestingly, IL1-B and TNF-a blood levels were associated with post-COVID-19 illness and the use of flavonoid-derived compounds could mitigate post-COVID-19 symptoms." (PMID 36838279, 2023). "In addition, severe COVID-19 causes an increase in proinflammatory mediators, such as IL-1, IL-6, and tumor necrosis factor-alpha (TNF-α), less CD4 interferon-gamma (INF-γ) expression, and fewer CD4 and CD8 cells, which enhance susceptibility to both bacterial and fungal infections inside the body." (PMID 36992139, 2023). "Both COVID-19 and RA exhibit an excessive immune response and cytokine imbalance, which are caused by the overactivation of T cells (especially Th1 and Th17 cells) that secrete a large number of cytokines, including TNF-α, IL-1β, IL-6, IL-8, IL-17, and GM-CSF, leading to tissue damage." (PMID 37163438, 2023). "Progression to severe COVID-19 is caused by hyperinflammatory responses characterized by exaggerated activation of myeloid cells, such as neutrophils and monocytes/macrophages, and the overproduction of proinflammatory cytokines, such as TNF, IL-6, and IL-1β6–9,12." (PMID 36941461, 2023). "Systemic and brain inflammation in patients with COVID-19 is associated with elevated levels of the same pro-inflammatory molecules that were increased following experimental dsRNA exposure in the current study, including IL-6, TNF-α, and complement C314,15,75." (PMID 37704739, 2023). "On the other hand, LPS or LPS + BG potently activated inflammatory cytokines, especially TNF-α, along with NFκB upregulation and ROS production, implying an influence of cytokine-associated NETosis, which might be a major mechanism of COVID-19-induced NETosis." (PMID 35406667, 2022). "Furthermore, COVID-19 dysbiosis causes an increase in inflammatory cytokines such as IL-6, TNF-α, and IL-1β, which might be one of the important predisposing factors for severe infection." (PMID 36532032, 2022). "IL-1β and TNFα are also potent activators of neutrophils that are attracted by IL-8 and release large amount of neutrophil extracellular traps (NETs) that are present in the sera of COVID-19 patients and are correlated with both progressive loss of lung functionality and thrombosis." (PMID 35563218, 2022). "Our data support this hypothesis, including the depressed monocyte surface expression of HLA-DR and CD86 reported here, and our previously published data demonstrating that COVID-19 is associated with decreased LPS-induced TNF-alpha production by peripheral blood mononuclear cells." (PMID 35421120, 2022). "It is assumed that the underlying mechanisms in COVID-19, such as acute respiratory distress syndrome, extensive lung damage, and cytokine release storm, such as IL-1, IL-6, and TNF-α leading to interstitial pulmonary inflammation, could have impacts on these autoimmune disorders." (PMID 35495619, 2022). "However, the association between the use of anti-TNFα antibodies and the onset of COVID-19 after vaccination remains unclear in the current survey because we could not measure antibodies against SARS-CoV-2 at this time." (PMID 35089397, 2022).
COVID-19 (continued). "In terms of biomolecular mechanisms, a number of factors in severe forms of COVID-19 are associated with a specific cytokine profile such as stimulation of interferon production, secretion of interleukin 2 and interleukin 7, granulocyte activation, and TNF production." (PMID 36016309, 2022). "Some DMARD treatments, such as hydroxychloroquine, anti-TNFα, and IL-6 inhibitors, have been employed during the COVID-19 pandemic to reduce the systemic inflammation associated with severe disease and are being studied for the prevention and/or treatment of COVID-19 and its complications." (PMID 35757699, 2022). "Moreover, inflammatory cytokines-TNF-α and IL-6, which may initiate mitochondrial ROS production and are associated with ATP production, were found in COVID-19 serum." (PMID 35281470, 2022). "The NIC-hLYS particles exhibited suppression of the inflammatory cytokines TNF-α and IL-6, which have been implicated in the development of more severe COVID-19, while elevating the production of the inflammatory cytokine IL-1β, which may contribute to enhanced antiviral activity." (PMID 33571320, 2021). "One explanation of the association between anti-TNF agents and a lower risk of ICU and death was that TNF-α played a part in the pathological process of COVID-19, including the promotion of Th1 cells and the induction of lymphocyte apoptosis, which led to a worse prognosis of COVID-19." (PMID 34335579, 2021). "The mechanism underlying the elevated COVID-19 mortality in patients with diabetes may be explained by the increase in chronic inflammatory markers, such as C reactive protein, interleukin 6, interleukin 10, and tumor necrosis factor-α, which promote susceptibility to COVID-19." (PMID 34940517, 2021). "In patients who are severely ill with COVID-19, the glycosylation of anti-spike IgG is changed, which can lead to pathology by over-activation of IgG effector functions, as we show here by particularly amplifying the production of COVID-19-associated cytokines such as IL-6 and TNF." (PMID 33979301, 2021). "Direct correlations between COVID-19 outcomes and individual cytokines and immune cell populations indicate symptoms of COVID-19 are associated with elevations in interleukin 1 beta (IL-1β), IL-6, interleukin 10 (IL-10), and TNFα), as well as a general lymphopenia." (PMID 33967944, 2021). "Indeed, patients with COVID-19 and vitamin D deficiency have been shown to exhibit significantly higher serum level of several inflammatory and coagulation biomarkers such as C-reactive protein, IL-6, TNF-α, ferritin, fibrinogen and D-dimer." (PMID 33906375, 2021). "Interestingly, biologics, other immune-modifying agents used to treat psoriasis by targeting specific pro-inflammatory proteins such as tumor necrosis factor (TNF), may increase risk for COVID-19." (PMID 33426009, 2020). "The decreased incidence of COVID-19 in patients treated with anti-TNFα and anti-proinflammatory ILs compounds underline the potential interest of these medications for further studies to open novel possible therapeutic strategies to avoid serious COVID-19 manifestations." (PMID 33519443, 2020). "Here, we describe severe COVID-19 to associate with autoantibodies against interleukin-1 receptor antagonist (IL-1Ra) and progranulin (PGRN), endogenous antagonists of IL-1 and TNF signaling, respectively." (PMID 42204159, 2026). "We further show that human intestinal organoids harboring the ATG16L1 risk allele exhibit heightened sensitivity to TNF and IFN co-stimulation and to serum from severe COVID-19 patients." (PMID 41648406, 2026). "Severe COVID-19 cases showed elevated IL-6, TNF-α, and IFN-γ, while asymptomatic individuals had broader, milder cytokine profiles." (PMID 41993206, 2026). "Significantly higher expression of IFN-γ (p = 0.0153), IL-6 (p < 0.0001), IL-10 (p < 0.0001), IL-17A (p = 0.0310), and TNF-α (p = 0.0034) was observed in COVID-19 patients compared to uninfected participants." (PMID 42023234, 2026).
COVID-19 (continued). "In serum samples, soluble TLR-2 and TLR-4, IL-1β, IL-4, IL-6, Il-10, IFN-α, and TNF-α levels were significantly decreased in patients with coronavirus disease-19 (COVID-19) as compared with other viruses (p < 0.05 in each)." (PMID 41766850, 2026). "Few studies have examined the functional spike-specific CD4+ and CD8+ T cell responses by evaluating IFN-γ-, IL-2, or TNF-α-producing T cells by flow cytometry in PwMS after the third dose of COVID-19 mRNA-vaccines." (PMID 41246331, 2025). "In the context of COVID-19, a cytokine storm—characterized by elevated interleukin-6 (IL-6), tumor necrosis factor-alpha (TNF-α), and C-reactive protein (CRP)—has been proposed as a contributing factor to dyslipidemia." (PMID 40565828, 2025). "This study was conducted to investigate the associations between polymorphisms in the TNF-α, IL-6, IL-8, IL-10, and CCL5 genes and COVID-19 severity." (PMID 40881695, 2025). "Critically ill COVID-19 patients frequently exhibit a cytokine storm, characterized by elevated levels of cytokines such as IL-6, IL-8, IL-12, TNFα, IL-17, MCP-1, IP-10, and IL-10." (PMID 40160814, 2025). "In severe cases of COVID-19, endothelial cells in the lung’s blood vessels are further activated by elevated levels of pro-inflammatory cytokines (IL-1, IL-6 and TNF) and ferritin, exacerbating a vicious cycle of immunothrombosis." (PMID 40612950, 2025). "Moreover, the anti-inflammatory properties of Febuxostat, through inhibition of the JAK/STAT and NF-κB pathways and subsequent reduction in pro-inflammatory cytokines such as IL-1β, IL-6, and TNF-α, may underlie its protective effects against COVID-19-related hyperinflammation and organ damage." (PMID 41235116, 2025). "We found up-regulation of TNF signaling via nuclear factor-κB (NF-kB) in patients with mild COVID-19, consistent with validated activation post infection." (PMID 40044970, 2025). "IL1B, IL6, and TNF are pro-inflammatory cytokines that contribute to the cytokine storm observed in severe COVID-19 cases, leading to acute respiratory distress and systemic inflammation." (PMID 41471341, 2025). "The benefits observed in the treated groups were associated with a substantial decrease in the levels of the pro-inflammatory cytokines IL-6 and TNF-α, which are key indicators of COVID-19 severity." (PMID 40868984, 2025). "Nonetheless, our study offers meaningful insight into the potential role of TNF-α inhibition in COVID-19 and underscores the urgent need for large, well-designed randomised trials to further clarify its therapeutic value and clinical implications." (PMID 40481519, 2025). "In COVID-19 patients treated with Empagliflozin, correlations were observed between IL-1, TNF-alpha, IL-6, and blood glucose levels." (PMID 40134446, 2025). "There is a substantial amount of data on cytokine storm syndrome in COVID-19 patients, particularly high circulating levels of IL-6, IL-10, IL-2R, IL-8, and TNF-α in COVID-19 patients with high mortality rates." (PMID 40508859, 2025). "The use of TNF-α inhibitors in SARS-CoV-2 patients is in line with current understanding of the pathophysiology of severe COVID-19." (PMID 40481519, 2025). "Targeted inhibition of IL-6 or TNF-α has therefore been proposed to mitigate ocular surface damage and preserve tissue integrity in COVID-19 patients." (PMID 39861857, 2025). "In COVID-19, the level of TNF-α in the blood is elevated, as monocytes, macrophages, B cells, T cells, and fibroblasts produce it to intensify inflammation." (PMID 39940645, 2025). "The pro-inflammatory cytokines IL-6 and TNF were found to be increased in both analyzed compartments (p ≤ 0.05) in patients who died from COVID-19." (PMID 41210940, 2025). "Although the precise mechanism of COVID-19 triggering SAPHO syndrome is still a mystery, rising interleukin and TNF-α levels, which can be caused by the virus, are mentioned in the pathogenesis of SAPHO syndrome." (PMID 40740959, 2025).